TLR4 (toll like receptor 4)
Diseases named in the same sentence as TLR4 in open-access papers (continued):
Sharing a sentence is not in itself a finding about the gene and the disease.
infection (continued). "Our results showed down-regulation of TLR4 after SE challenge at both 1 h and 4 h post-infection, this being significantly attenuated following the inhibition of NF-kB 1 expression." (PMID 21637513, 2009). "Correspondingly, flow cytometry analysis also revealed increased level of cell surface density of TLR2 and TLR4 in B. pseudomallei- infected cells at 24 h post infection." (PMID 19806192, 2009). "Immune response-associated genes, with altered expression in virulent strain infection, were selected for further investigation: Tlr2, Tlr4, Tlr13, Myd88, Il1b, Il6, dectin-2 and Cxcl12." (PMID 19845042, 2009). "Yersinia and Pseudomonas species also modulate their LPS structures, resulting in diminished TLR4 responses to infection." (PMID 19169359, 2009). "In an in vivo study, the TLR4 mRNA expression was markedly increased in the cornea of Balb/c mice after infection by Pseudomonas aeruginosa." (PMID 19960069, 2009). "With SE challenge, TLR4 expression was down-regulated at both 1 h (-1.75 - fold) and 4 h (-3.45 - fold) post-infection." (PMID 21637513, 2009). "Upon infection with B. pseudomallei, the expression levels of TLR2 and TLR4 increased gradually and a significant up-regulation compared to control cells was observed at 24 h post infection (p<0.05)." (PMID 19806192, 2009). "TLR4 was required for control of infection in the bladder, as TLR4−/− mice had ∼1.5-log more wild type bacteria in the bladder at 24 h compared to B6 mice, which correlated with a loss of PMN recruitment in the TLR4−/− mice." (PMID 19057665, 2008). "While both strains of mice lost body temperature in response to vaccinia infection, temperatures decreased to a greater extent over the course of the infection in C3H/HeJ (TLR4 mutant) mice relative to C3HeB/FeJ." (PMID 18802464, 2008). "Day 5 is near the peak of the infection where differences between TLR4 mutant and control mice are most pronounced." (PMID 18802464, 2008). "Together, in bronchial LN cells functional Tlr4 results in a higher Th1/Th17 response after infection." (PMID 18498620, 2008). "In placebo-treated animals, the levels of TLR4 mRNA remained relatively unchanged during infection, but TLR4 mRNA expression was still decreased in animals of both dexamethasone-treated groups by day 1 postinfection." (PMID 19049646, 2008). "Collectively, these data show an important role for Tlr4 in infection, being bacterial clearance, induction of pro-inflammatory cytokines, and induction of Th1 and Th17 responses." (PMID 18498620, 2008). "Bioluminescence imaging showed that C3H/HeJ (TLR4 mutant) mice had significantly greater viral replication in the chest region on days 1, 4, and 5 post-infection (p<0.05)." (PMID 18802464, 2008). "TLR4 can however exert different immunological effects as demonstrated by studies showing diverse effects of TLR2 and TLR4 in infection and tissue injury models." (PMID 18974879, 2008). "In short, functional Tlr4 results in a lower lung inflammatory response after infection, a higher inflammatory response and Th1/Th17 response after wP vaccination and challenge, and a lower Th2 response after wP and aP vaccination and challenge." (PMID 18498620, 2008). "Previous studies provided evidence for the role of the gene coding for Toll-like receptor 4 (TLR4) in both the infection process (in mice), and the response to vaccination (in mice and men)." (PMID 18987746, 2008). "At the peak of infection on day 6, the chest luminescence of the TLR4 mutant mice was 8-fold higher than that of the control mice." (PMID 18802464, 2008). "Functional Tlr4 also results in a higher TNF-α response after infection, and after wP vaccination and challenge." (PMID 18498620, 2008). "Surprisingly, the TLR4 mutant mice lost slightly less weight than the controls with significant differences on days 1–3 and 7–8 post-infection (p<0.05)." (PMID 18802464, 2008).
infection (continued). "In the context of a natural infection, recognition of FimH by TLR4 is important for the host to mount an innate immune response against uropathogenic E. coli." (PMID 19057665, 2008). "Nonetheless, increased NOD2 levels, which correlate with TLR2 and TLR4 expression, were noted in some patients with severe infection." (PMID 17705850, 2007). "TLR4 and IL-12Rβ1 signaling: An immediate response to pathogens is essential for host defense during the early stages of infection." (PMID 23675015, 2007). "MD2 was induced in response to pro-inflammatory cytokines and bacterial products, while MD2 expression in A549 cells is enhanced along with TLR4 following infection with RSV." (PMID 16219107, 2005). "TLR4−/− mice showed variable responses to the challenge with M. tuberculosis, with either normal resistance to infection or chronic pneumonia and increased mortality." (PMID 16322770, 2005). "pylori infection by inhibiting ferroptosis through modulation of the HMGB1/TLR4 pathway." (PMID 42004898, 2026). "Furthermore, the infection sensitizes epithelial cells by upregulating the expression of Toll-like receptor 4, a key receptor that mediates S100A8/A9 signaling." (PMID 41853711, 2026). "Innate immune detection of pathogen- and danger-associated molecular patterns (PAMPs/DAMPs) centres on pattern-recognition receptors, with the TLR4/MD-2 complex being uniquely sensitive to trace levels of lipopolysaccharide (LPS) as well as infection-triggered endogenous ligands." (PMID 41835451, 2026). "Importantly, this infection duration noted here with low inoculums of modern respiratory isolates in tlr4 mutant mice is the longest reported for A. baumannii in any animal model to date." (PMID 40817088, 2025). "In our intravenous infection model, bacteria directly enter the bloodstream and encounter systemic immune responses before reaching the brain, which may trigger distinct TLR4-dependent inflammatory cascades." (PMID 40821830, 2025). "Physiologically, this action may enable the cell to enhance IFN response when an intracellular infection, which activates cGAS, is concomitant with the presence of bacterial material outside the cell, activating TLR4." (PMID 40806167, 2025). "This could potentially be due to the inhibition of TLR4-mediated immune response, which is indispensable for combating infection." (PMID 40421030, 2025). "MyD88/NF-kB signaling is a key downstream target of TLR4 activation during infections." (PMID 40791819, 2025). "In contrast, mutants that lack hydroxylation at LpxO2-specific lipid A sites, a mutation that has been shown to occur during chronic CF infection, inhibit TLR4/MD-2-dependent cytokine signaling, with surprisingly little change in the severity of infection in mice." (PMID 40512027, 2025). "One mechanism described how leptospiral-LPS activates murine, but not human, TLR4 in cultured macrophages, and it is associated with resistance to infection." (PMID 39975062, 2025). "C. perfringens abundance was increased in NEC piglets and activation of TLR4 by Clostridia may occur in NEC as infection induced host immune responses involving TLR4/MyD88/NF-κB signaling pathways in piglets." (PMID 41283989, 2025). "Evidence for NMI and IFI35 (in M2) indicates that they function as damage-associated molecular patterns in the extracelluar space, mediating proinflammatory responses to cellular infection and damage through the activation of the nuclear factor-κB in the Toll-like receptor 4 signalling pathway." (PMID 40656995, 2025). "The results suggest that TLR4 may be temporally activated at early infection, but decreased with long-term or high burden Mtb infection." (PMID 40502714, 2025). "Furthermore, the expression of TLR4, IL-1β, IL-6, and IL-10 was up-regulated at 24 h post infection in the common carp (Cyprinus carpio) spleen in response to A. hydrophila." (PMID 40298788, 2025).
infection (continued). "Notably, time-of-addition experiments revealed that TAK-242 is most effective when administered before or during CHIKV infection, indicating that TLR4 plays a pivotal role in the early stages of infection, specifically during viral attachment and/or entry." (PMID 40872941, 2025). "One study described how leptospiral-LPS activates murine, but not human, TLR4 in cultured macrophages, and it is associated with resistance to infection." (PMID 40445994, 2025). "Screening for recipient susceptibility genes such as TLR4, NOD2, and DEFB, in combination with donor infection-related indicators like CMV serostatus, enables the classification of recipients into low-, intermediate-, or high-risk categories for infection." (PMID 41550938, 2025). "Furthermore, FEBF effectively suppressed the PRV-induced upregulation of TLR4, MyD88, and NF-κB p65 proteins between 36 and 48 h post-infection." (PMID 40308697, 2025). "In addition to playing a significant role during murine infection, TLR4 is relevant in clinical settings as well." (PMID 40817088, 2025). "SAA3 interacts with TLR2 and/or TLR4 to regulate post-infection immune responses." (PMID 40791819, 2025). "While previous reviews have catalogued individual virulence factors—such as the VirB type IV secretion system—and their actions on pathways like TLR4 signaling, most analyses focus on isolated stages or mechanisms, overlooking the integrated, dynamic regulation spanning the entire infection course." (PMID 41583483, 2025). "The study found that polymorphisms in the TLR4 gene (rs4986790), IL-10 gene (rs1800896), TNF-α gene (rs1800629), and MBL2 gene (rs1800450) were significantly associated with patients’ susceptibility to infection, disease severity, and prognosis." (PMID 40692949, 2025). "To investigate the role of TLR4 in the infection of PAMs by G. parasuis, we designed TLR4 siRNA." (PMID 40427234, 2025). "Upon release into the host circulation, either during bacterial lysis or infection, LPS triggers a potent inflammatory response primarily by activating Toll-like receptor 4 (TLR4) on immune and parenchymal cells, especially Kupffer cells and liver sinusoidal endothelial cells." (PMID 41296418, 2025). "Our study confirms that hyporesponsivenes to tlr4 results in lethal infection in C3H-HeJ mice." (PMID 39975062, 2025). "Finally, we screened a third modern respiratory isolate, G803, which is phylogenetically and geographically unrelated to G636 and G654, for its ability to establish long-term infection with a 105 inoculum in tlr4 mutant mice." (PMID 40817088, 2025). "Moreover, we found that inhibiting TLR4 further aggravated the disruption of tight junction protein during infection." (PMID 40821830, 2025). "Compared with CD11b+Mø, CD11b-Mø expressed a higher level of TLR4, suggesting that CD11b−Mø may have a strong ability to resist infection." (PMID 40237529, 2025). "Likewise, HBV+DEN-treated liver showed elevated high-mobility group box 1 (HMGB1) expression, a well-known damage-associated molecular pattern (DAMP) molecule and TLR4 agonist, in hepatocytes compared with Sham+DEN-treated liver at 4 months post-infection." (PMID 40579434, 2025). "Additionally, microparticles released from iRBCs and heme produced during infection can activate TLR4, triggering the MAPK and NF-κB signaling pathways and inducing the production of cytokine and chemokine." (PMID 41398915, 2025). "Upon infection with E. coli, the Toll-like receptor 4 (TLR4)/nuclear factor kappa-B (NF-κB) and mitogen-activated protein kinase (MAPK) signaling cascades are promptly activated within the endometrium of cows, resulting in the elevated production of pro-inflammatory cytokines." (PMID 40075974, 2025).
infection (continued). "Mouse models of infection with a number of viruses have been reported to show TLR4-dependent pathology defined using either TLR4 knockout mice or inhibitors, including respiratory syncytial virus (RSV), influenza virus, Japanese encephalitis virus, Ebola virus and Marburg virus." (PMID 41218088, 2025). "The strongest association between TLR4 polymorphisms and disease susceptibility has been demonstrated with respiratory syncytial virus (RSV) infection, with newborns heterozygous for Asp299Gly and Thr399Ile being more susceptible to infection." (PMID 41295183, 2025). "Interestingly, BBB disruption is at least partially mediated by toll-like receptor 4 (TLR4), as TLR4 knockout (KO) mice have decreased BBB permeability following VEEV TC-83 infection." (PMID 40005568, 2025). "Both TLR4 and NF-κB mRNA levels were significantly (p < 0.05) elevated in a time-dependent manner following infection, with NF-κB showing a peak 13.4-fold increase at 48 h and TLR4 reaching a maximum 7.4-fold induction at 72 h compared with uninfected controls." (PMID 41294830, 2025). "For instance, miR-302b is caused by Toll-like receptor 2 (TLR2) and TLR4 through the ERK-p38-NF-κB signaling pathway during infection with the Gram-negative bacterium Pseudomonas aeruginosa." (PMID 40005551, 2025). "Moreover, the Feline Infectious Peritonitis Virus (FIPV) has been shown to activate TLR4-mediated autophagy to sustain its replication within feline macrophages, thus evading the host’s innate immune response and prolonging the infection." (PMID 39599901, 2024). "We believed that there might be an initial factor that increases inflammation by increasing the gene expression level of proinflammatory cytokines by activating the HMGB1/TLR4/RAGE/NF‐κB pathway due to infection." (PMID 39046369, 2024). "In our investigations into the role of TLR2 and TLR4 in the activity of MDSCs, we also employed three distinct approaches: the use of wild-type cells, receptor blockade, and validation of results using cells from receptor knockout mice and in vivo infection." (PMID 39035356, 2024). "implicated that trimeric spike proteins from SARS‐CoV‐2 or SARS‐CoV could elicit an anti‐bacterial‐like response at the early stage of infection through TLR4 or TLR4‐related signalling pathways." (PMID 39166890, 2024). "Furthermore, kaempferol fully restores the activity of ceftiofur in animal infection models by relieving the TLR4/NF-κb pathway." (PMID 39723150, 2024). "Previous studies identified the importance of lipopolysaccharide (LPS) engagement of TLR4 in the clearance of Pa infections, and thus we hypothesized that the use of a TLR4 agonist would enhance an antibody response specific to CoaB." (PMID 38400099, 2024). "Not only inhibition of this transcriptional plasticity through interference with RNA polymerase activity but also blockade of TLR4 sensing and its downstream signaling hubs, including NF-κB and MyD88, swiftly dampened infection-driven neutrophil shifts and subsequent phenotypic changes." (PMID 38517968, 2024). "Furthermore, the role of PE_PGRS38 in TLR4/NF-ĸB-dependent inflammation, the inflammasome, and apoptosis during infection has remained elusive." (PMID 38785795, 2024). "However, the expression of TLR4 was upregulated in the peripheral blood mononuclear cells (PBMCs) of water buffaloes during early infection with Fasciola gigantica." (PMID 39679172, 2024). "Furthermore, the immunofluorescence results of the lungs of mice show that PE_PGRS38 downregulated the expression of TLR4 and p-NF-κB during infection." (PMID 38785795, 2024). "Reduced TLR4 expression might affect the immune response of COPD patients to infection, as bacterial LPS bind and activate the TLR4." (PMID 38641747, 2024). "TLR4 involvement during the infection was also observed through mediating IL6 and TNFα." (PMID 39729468, 2024).
infection (continued). "As the results described in this paper confirm, CD14 gene expression is increased by LPS in alveolar macrophages after several hours of infection, TLR4 gene expression is decreased by LPS infection of mouse macrophages, and MD2 gene expression is higher after LPS infection of alveolar macrophages." (PMID 38785798, 2024). "Furthermore, TLR-4 at the cell membrane binds to its bacterial LPS ligand and recruits myeloid-differentiating factors, like MyD88, for an infection-induced inflammatory cascade." (PMID 39202716, 2024). "Finally, during infection, lipid A signals through the pattern-recognition receptor TLR4 and coordinating protein MD-2 present on host innate immune cells." (PMID 38131669, 2024). "In M1 pro-inflammatory-like macrophages, m6A was found in transcripts that are highly expressed and translated during macrophage response to infection including TLR4 (Toll-Like Receptor 4), ICAM1 (Intracellular Adhesion Molecule 1) and YAP1 (Yes-associated protein 1)." (PMID 38780787, 2024). "Moreover, the increased expression of TLR4 in the lungs of Mettl3 cKO mice upon infection with P. multocida and of TLR2 upon infection with S. aureus and M. pneumoniae were confirmed by immunohistochemistry staining." (PMID 38182816, 2024). "Next, to investigate whether CATH-1-mediated inhibition of SS2-induced cytokine production is dependent on TLR2/4, the expression of TLR2 and TLR4 was detected through pre-incubation CATH-1 with cells 2 h prior to SS2 infection." (PMID 37605242, 2023). "Interestingly, our DSP analysis of hamster lung tissues showed that the MyD88-independent/TRIF-dependent TLR4 pathway was the top enriched TLR4 cascade after two days of infection." (PMID 37369668, 2023). "The secreted nature of EhaF prompted us to test if EhaF-containing supernatant fraction itself is sufficient to suppress proinflammatory responses by pretreating BMDMs with supernatant from BL21/pEhaF-FLAG or BL21/pEmpty prior to infection or treatment with TLR4 stimuli." (PMID 37041208, 2023). "Previous studies have shown that the important immune response of the organism to LPS infection is the activation of the TLR4 gene, which responds to LPS present in tissues and the bloodstream and triggers a pro-inflammatory response that promotes the eradication of invading bacteria." (PMID 37175446, 2023). "Extracellular MRP8/14, which is a heterodimeric complex released by phagocytes during infection, acts as an endogenous alarmin that amplifies the TLR4 signaling-dependent inflammatory response by inducing proinflammatory cytokines, such as TNF-α, IL-1β, IL-12 and IL-18." (PMID 37701855, 2023). "However, in vitro infection of macrophages deficient in TLR2, TLR4, and MyD88 by L. amazonensis is higher than wild-type counterparts." (PMID 37000792, 2023). "Taking into account the host’s immune status, the TLR4 gene expression was statistically higher in the skin of amoeba-infected mice with normal immunity (A) than in amoeba-infected hosts with reduced immunity (AS) at the beginning of the infection." (PMID 37242301, 2023). "As a result, the vaccine-TLR4 complex may trigger the TLR4-dependent signaling pathways that protect against the infection of Leishmania." (PMID 36851219, 2023). "TLR4 is particularly significant due to its ability to integrate a variety of diverse pro-inflammatory triggers, including endogenous agents released during cell senescence or following injury or infection." (PMID 37867523, 2023). "Meanwhile, dietary EOA treatment also upregulated CLDN-1, OCLN, ZO-1, MUC2 and FABP2 mRNA levels at the middle infection phase, as well as linearly reduced the gene expression level of TLR4, NF-κB and IL-1β at the early infection stage in infected broiler chickens." (PMID 37391807, 2023).